MATN3 (matrilin 3)
Description:
Major component of the extracellular matrix of cartilage and may play a role in the formation of extracellular filamentous networks.
Synonyms: EDM5; HOA; DIPOA; OADIP; OS2; SEMDBCD
Tractability: Antibody: its Gene Ontology location is reachable by antibodies, with high confidence; UniProt places it where antibodies can reach, with medium confidence; UniProt predicts a signal peptide or a membrane-spanning region.
Gene: Protein-coding gene on chromosome 2 (19,992,052 to 20,012,669, reverse strand). Ensembl gene ENSG00000132031.
Subcellular location: Secreted
Subcellular location (Human Protein Atlas): Endoplasmic reticulum; Golgi apparatus; Vesicles; Predicted to be secreted
Pathways (Reactome):
Metabolism of proteins: Post-translational protein phosphorylation; Regulation of Insulin-like Growth Factor (IGF) transport and uptake by Insulin-like Growth Factor Binding Proteins (IGFBPs)
Extracellular matrix organization: ECM proteoglycans
Gene Ontology:
Molecular function: protein binding; extracellular matrix structural constituent; calcium ion binding
Biological process: extracellular matrix organization; skeletal system development
Cellular component: matrilin complex; endoplasmic reticulum lumen; extracellular matrix; extracellular region; non-collagenous component of interstitial matrix
Genetic constraint (gnomAD): Loss-of-function variants: 40 observed, 38.35 expected, observed/expected ratio (o/e) 1.04, 90% interval 0.81 to 1.36. The upper end of that interval is the gene's LOEUF score, 1.36, which puts it in group 5 of 6, group 1 being the genes least tolerant of losing a copy. Missense variants: 568 observed, 577.99 expected, observed/expected ratio (o/e) 0.98, 90% interval 0.92 to 1.05. Synonymous variants: 205 observed, 220.04 expected, observed/expected ratio (o/e) 0.93, 90% interval 0.83 to 1.05.
Homologues: Orthologues: chimpanzee MATN3 (99% identical), macaque MATN3 (94% identical), pig MATN3 (86% identical), dog MATN3 (86% identical), mouse Matn3 (82% identical), rat Matn3 (82% identical), rabbit MATN3 (76% identical), guinea pig MATN3 (73% identical), tropical clawed frog matn3 (43% identical), zebrafish matn3b (39% identical), zebrafish matn3a (37% identical). Paralogues in human: MATN2 (39% identical), MATN4 (36% identical), MATN1 (34% identical), COL12A1 (22% identical), COL6A3 (20% identical), COL14A1 (19% identical), COL6A6 (17% identical), VWA2 (16% identical), COL6A5 (16% identical), COCH (14% identical), VIT (14% identical), VWA1 (13% identical).
Diseases named in the same sentence as MATN3 in open-access papers:
MATN3 is named in the same sentence as 59 diseases in open-access papers, as found by Europe PMC text mining. Sharing a sentence is not in itself a finding about the gene and the disease. The quoted sentences say what the papers report.
multiple epiphyseal dysplasia (26 papers, 2008 to 2025). Multiple epiphyseal dysplasias (MED/EDMs) are characterized by epiphyseal anomalies causing joint pain early in life, recurrent osteochondritis and early arthrosis. "Genetic and imaging testing confirmed his diagnosis of multiple epiphyseal dysplasia due to Matrilin-3 pathogenic variants." (PMID 38800255, 2024). "Herein, we report a case of a middle-aged man with bilateral knee joint locking symptoms who was diagnosed with multiple epiphyseal dysplasia caused by Matrilin-3 (MATN3) pathogenic variants and was successfully treated with arthroscopic loose body removal." (PMID 38800255, 2024). "Among the patients in categories 1–3 in this study, pathogenic variants were found in genes such as COL2A1, COMP, and MATN3, which are the causative genes of type II collagenopathy and multiple epiphyseal dysplasia (MED)." (PMID 34122524, 2021). "Mutations in matrilin-3 in humans can cause many kinds of skeletal diseases, such as multiple epiphyseal dysplasia and early-onset osteoarthrosis." (PMID 34136064, 2021). "Mutations in human MATN3 are associated with a variety of skeletal diseases including multiple epiphyseal dysplasia (MED), spondylo-epi-metaphyseal dysplasia (SEMD), and osteoarthritis (OA), underscoring its importance in cartilage development and homeostasis." (PMID 22967398, 2012). "Mutations in matrilin 3 can result in multiple epiphyseal dysplasia (MED), a disease characterized by delayed and irregular bone growth and early-onset osteoarthritis." (PMID 22083516, 2012). "Mutations of matrilin-3 have been reported in a variety of skeletal diseases, including multiple epiphyseal dysplasia which is characterized by irregular ossification of the epiphyses and early-onset osteoarthritis, spondylo-epi-metaphyseal dysplasia, and idiopathic hand osteoarthritis." (PMID 24741569, 2014). "Previous studies on COMP mutations have shown mutant COMP is co-localized with chaperone proteins, and we have reported an unfolded protein response (UPR) in mouse models of PSACH-MED (multiple epiphyseal dysplasia) harboring mutations in Comp (T585M) and Matn3, Comp etc (V194D)." (PMID 22006726, 2012). "Interestingly, the mouse model for multiple epiphyseal dysplasia, which specifically expresses a mutation in matrilin-3, was reported to induce CRELD2 mRNA expression and other ER-stress inducible genes as the symptoms progressed." (PMID 21106106, 2010). "Missense mutations in the VWFA domain of matrilin-3 have been observed in patients with multiple epiphyseal dysplasia (MED)." (PMID 27104523, 2016). "In spondyloepimetaphyseal dysplasia (SEMD) and multiple epiphyseal dysplasia (MED), mutations in the matrilin-3 gene cause an aberrant response towards TGF-β and differentiation of ATDC5 chondroprogenitor cells." (PMID 27104523, 2016). "Mutations in genes encoding cartilage oligomeric matrix protein and matrilin-3 cause a spectrum of chondrodysplasias called multiple epiphyseal dysplasia (MED) and pseudoachondroplasia (PSACH)." (PMID 25693198, 2015). "Studies have shown that mutations in the matrilin-3 gene (MATN3) are associated with multiple epiphyseal dysplasia (MED) and spondyloepimetaphyseal dysplasia (SEMD)." (PMID 25196597, 2014). "This is indicated by the recent identification of the mutations of MATN-3 in multiple epiphyseal dysplasia (MED) patients." (PMID 18518980, 2008). "Mutations in the vWF A domain of matrilin-3 cause multiple epiphyseal dysplasia (MED), however the pathological mechanism remains to be determined." (PMID 18518980, 2008). "A 7-year-old girl (proband 1; P1), the only child in the family, was referred to a geneticist due to progressive lower limb deformities and suspicion of MATN3-related multiple epiphyseal dysplasia (MATN3-MED)." (PMID 40725227, 2025). "The mutation of MATN3 gene may lead to some diseases such as multiple epiphyseal dysplasia (MED), epiphyseal dysplasia (BHMED), and epiphyseal dysplasia of the vertebral body (SEMD)." (PMID 34900024, 2021).
multiple epiphyseal dysplasia (continued). "In humans, nine missense mutations in the matrilin-3 gene (MATN3) that affect the vWFA domain (typically the β-sheets) have been found in patients with multiple epiphyseal dysplasia (MED), characterized by delayed and irregular ossification of the epiphyses and early-onset osteoarthritis." (PMID 22973175, 2012). "Armet is a robust UPR marker, inducible in vitro with chemical ER stressors, as well as in the brain following experimentally induced ischemia, or by misfolding Matn3 expressed in a mouse model of multiple epiphyseal dysplasia." (PMID 21935428, 2011). "Multiple epiphyseal dysplasia (MED) and matrilin type spondyloepimetephyseal dysplasia (SEMD, matrilin type) are two forms of chondrodysplasia associated with mutations in the matrilin-3 (MATN3) gene." (PMID 25196597, 2014). "The function of Creld2 is unknown, however it was shown to be highly upregulated, along with Armet, in a Matn3 mutant model of multiple epiphyseal dysplasia." (PMID 21935428, 2011). "For example, mutations in ECM genes encoding collagen IX, matrilin-3 and cartilage oligomeric matrix protein (COMP) result in multiple epiphyseal dysplasia (MED) and pseudoachondroplasia (PSACH)." (PMID 25693198, 2015). "Pseudoachondroplasia (PSACH) and multiple epiphyseal dysplasia (MED) are skeletal disorders resulting from mutations in COMP, matrilin-3 or collagen IX and are characterised by short-limbed dwarfism and premature osteoarthritis." (PMID 24312420, 2013). "It remains unknown whether Xbp1 splicing, Atf6 proteolysis, or Eif2α phosphorylation occur in other mouse models of skeletal dysplasias characterized by ER stress, including the p.V194D Matn3 mutant model of multiple epiphyseal dysplasia, and an Aga2-mutant model of osteogenesis imperfecta." (PMID 21935428, 2011). "The role of ER stress in GSDs might best be exemplified by mutations in COMP, matrilin-3 and type X collagen resulting in pseudoachondroplasia (PSACH), multiple epiphyseal dysplasia (MED) and metaphyseal chondrodysplasia type Schmid (MCDS), respectively." (PMID 26635999, 2015). "Mutant matrilin-3 (V194D) forms non-native disulphide bonded aggregates in the rER of chondrocytes from cell and mouse models of multiple epiphyseal dysplasia (MED)." (PMID 23956175, 2013).
osteoarthritis (20 papers, 2012 to 2025). A noninflammatory degenerative joint disease occurring chiefly in older persons, characterized by degeneration of the articular cartilage, hypertrophy of bone at the margins and changes in the synovial membrane. "Previous studies have implicated MATN3 in the development and progression of osteoarthritis and its potential role in gastric cancer invasion." (PMID 39991588, 2025). "Mutations in the Matrilin-3 gene have emerged as key contributors to osteoarthritis, a degenerative joint condition." (PMID 38665758, 2024). "Understanding the role of MATN3 mutations in osteoarthritis is crucial for developing targeted therapies and interventions to mitigate the progression of this debilitating condition." (PMID 38392197, 2024). "Mutations in the Matrilin-3 gene (MATN3) have been identified as significant factors in the development of osteoarthritis, a progressive joint disease." (PMID 38392197, 2024). "Matrilin-3 mutations have been particularly associated with early-onset osteoarthritis, typically affecting the hands, knees, and spine." (PMID 38392197, 2024). "Understanding the role of Matrilin-3 mutations in osteoarthritis will allow us to identify at-risk individuals and develop targeted interventions against this debilitating condition." (PMID 38665758, 2024). "Matrilin-3 mutations have been linked with early-onset osteoarthritis, primarily affecting joints in the hands, knees, and spine." (PMID 38665758, 2024). "The exact mechanisms by which Matrilin-3 mutations contribute to the pathogenesis of osteoarthritis are still under investigation." (PMID 38392197, 2024). "In humans, chondrodysplasia-causing mutations in COMP, collagen IX, or MATN3 are frequently associated with premature osteoarthritis." (PMID 31963938, 2020). "Mutations of matrilin-3 in humans are closely related to many kinds of skeletal disease, including osteoarthritis, emphasizing its importance in the development and homeostasis of cartilage." (PMID 29483929, 2018). "Mutations in matrilin-3 are associated with disorders in skeletal development and predisposes individuals to develop osteoarthritis." (PMID 27104523, 2016). "As a result, matrilin-3 null mice are predisposed to the initiation and progression of osteoarthritis." (PMID 27104523, 2016). "Further study with a larger population size remains to be conducted for a definitive affirmation of correlates of MATN3 gene polymorphism in osteoarthritis patients." (PMID 22973175, 2012). "MATN3 is a cartilage-specific matrix protein, mutations in which result in early-onset osteoarthritis." (PMID 22808055, 2012). "Our study is the first to analyze the distribution of polymorphisms of MATN3 gene in a group of Chinese osteoarthritis patients and unrelated healthy controls." (PMID 22973175, 2012). "So our results better evaluate the relationship between the MATN3 polymorphism and osteoarthritis, especially the subtype of OA." (PMID 22973175, 2012). "Thirdly, lack of original data for each patient with his or her Kellgren-Lawrence grade limited our further analysis of the relationship between the MATN3 gene polymorphism and the severity of osteoarthritis." (PMID 22973175, 2012). "Based on our findings, we believe that the levels of miR-448 and matrilin-3 could be considered as biomarkers for a diagnostic index of osteoarthritis." (PMID 29483929, 2018). "However, these matrilin-3 null mice exhibit increased susceptibility to osteoarthritis during ageing." (PMID 27104523, 2016). "Polymorphisms and mutations in several genes, such as transforming growth factor β (TGF-β), bone morphogenetic protein (BMP), growth differentiation factor 5 (GDF5), secreted frizzled-related protein 3 (FRZB), and matrilin-3 (MATN3) predisposes individuals to early-onset osteoarthritis." (PMID 27104523, 2016). "Interestingly, despite these attributes, matrilin-3 induces osteoarthritis-associated markers in chondrocytes in a concentration-dependent manner." (PMID 27104523, 2016).
osteoarthritis (continued). "In conclusion, our results suggest that the investigated polymorphism in the MATN3 gene might play a role in osteoarthritis in the Han population." (PMID 22973175, 2012). "The level of miR-448 was significantly higher and matrilin-3 expression was significantly lower in osteoarthritis cartilage and IL-1β-induced chondrocytes than in normal tissues and cells." (PMID 29483929, 2018). "In this study, the mRNA and protein levels of matrilin-3 in osteoarthritis cartilage were respectively detected using quantitative real-time PCR and western blot." (PMID 29483929, 2018). "The findings showed that miR-448 contributed to the progression of osteoarthritis by directly targeting matrilin-3." (PMID 29483929, 2018). "Earlier studies have also demonstrated that the expression of matrilin-3 is dramatically lower in osteoarthritis cartilage than in normal cartilage." (PMID 29483929, 2018). "Our data demonstrate that the matrilin-3 expression was dramatically reduced in osteoarthritis cartilage, which is consistent with previous findings." (PMID 29483929, 2018). "Our data show that the miR-448 level significantly increased and the expression of matrilin-3 significantly decreased in osteoarthritis cartilage compared to normal cartilage." (PMID 29483929, 2018). "We transfected human osteoarthritis chondrocytes with an miR-448 mimic or inhibitor, expressions of matrilin-3, aggrecan, type II collagen and MMP-13 were determined using western blot, quantitative real-time PCR and ELISA assays as appropriate." (PMID 29483929, 2018). "Our findings demonstrate that miR-448 inhibition directly upregulated matrilin-3 expression, protecting IL-1β-induced and osteoarthritis chondrocytes from ECM degradation." (PMID 29483929, 2018). "In this study, the data show that matrilin-3 was evidently reduced in osteoarthritis cartilage compared to normal cartilage." (PMID 29483929, 2018). "It revealed a significant inverse correlation between matrilin-3 and miR-448 in osteoarthritis cartilage." (PMID 29483929, 2018). "Existing data provide insights into the critical role of matrilin-3 in inflammation, matrix degradation, and matrix formation in cartilage development and osteoarthritis." (PMID 27104523, 2016). "It has been found that enhanced matrilin-3 gene and protein expression was correlated with the extent of tissue damage in osteoarthritis patients." (PMID 22973175, 2012). "Deletion or mutation of the gene encoding the cartilage extracellular matrix (ECM) protein matrilin-3 (MATN3) results in the early onset of osteoarthritis (OA), suggesting chondroprotective properties of MATN3." (PMID 22967398, 2012). "ADMED can be due to; COMP (cartilage oligomeric matrix protein), COL9A1-COL9A3 (collagen type IX alpha 1–3 chain) or MATN3 (matrilin 3) and presents in childhood with joint pain, exercise-induced fatigue, restricted mobility, short stature, and early-onset osteoarthritis." (PMID 34092239, 2021). "This study focuses on whether miR-448 plays a significant role in progression of osteoarthritis by targeting matrilin-3." (PMID 29483929, 2018). "Thus, miRNAs and matrilin-3 clearly both have the important roles in the pathogenesis of osteoarthritis." (PMID 29483929, 2018). "Therefore, in this review, we discuss the initiation and progression of osteoarthritis, and the role of matrilin-3 in maintaining cartilage structure, function, and disease development." (PMID 27104523, 2016). "Interestingly, the expression of matrilin-3 is increased in osteoarthritis and its expression levels are correlated with disease severity." (PMID 27104523, 2016). "Some researchers found that functional knockout of MATN3 in mice could induce premature hypertrophy of articular chondrocytes which could contribute to the development of osteoarthritis in adult mice." (PMID 22973175, 2012).
osteoarthritis (continued). "MiR-483 is known to target tissue inhibitors of metalloproteinases 2 (TIMP2), and a recent study suggests that inhibition of miR-483-5p by intra-articular injection of antago-miR-483-5p could prevent the onset of osteoarthritis (OA) pathogenesis by targeting Matrilin 3 (Matn3) and TIMP2." (PMID 36980601, 2023). "Consequently, it was speculated that increased miR-448 regulated the progression of osteoarthritis via decreasing matrilin-3 expression." (PMID 29483929, 2018). "However, these procedures do not guarantee prevention of early onset osteoarthritis of the knee because the cartilage matrix defect originates from mutations of either MATN3 or COMP." (PMID 24629099, 2014). "In this study, we investigated the role of matrilin-3 in preventing Ad-MSC-derived chondrocyte hypertrophy in vitro and in an osteoarthritis (OA) destabilization of the medial meniscus (DMM) model." (PMID 33255398, 2020). "The results suggest that introduction of miR-448 downregulated matrilin-3, thereby inhibiting ECM synthesis of chondrocytes and resulting in the progression of osteoarthritis." (PMID 29483929, 2018). "Knockdown of miR-448 significantly increased the expressions of matrilin-3, aggrecan and type II collagen, and decreased the expression of MMP-13 compared with osteoarthritis chondrocytes transfected with anti-miR-NC." (PMID 29483929, 2018). "Matrilin-3 can regulate bone ECM components as evidenced by its expression in bone under normal conditions and its increased levels during osteoarthritis." (PMID 27104523, 2016). "Here, we discuss the vital role of matrilin-3, an ECM protein involved in cartilage development and potential osteoarthritis pathomechanisms." (PMID 27104523, 2016). "In these studies, the investigators described MATN3-MED patients as having slightly short or normal stature, complaints in early childhood at knee and hip joints, and early onset osteoarthritis." (PMID 24629099, 2014). "The changes in expression of the DEGs listed in the osteoarthritis pathway included strong down-regulation of cartilage matrix molecules (COL2A1, MATN3, and ACAN) and up-regulation of matrix proteases (ADAMTS5 and MMP13) and apoptosis-related molecules (CASP4)." (PMID 32294904, 2020). "Previously, we had not observed age-associated osteoarthritis in single MATN1, MATN2, MATN3, or double MATN1/MATN3 deficient mice." (PMID 31963938, 2020). "The findings suggested that introduction of miR-448 significantly decreased the protein expression of matrilin-3 and the mRNA levels of aggrecan and type II collagen, and enhanced the secreted protein expression of MMP-13 compared with osteoarthritis chondrocytes transfected with miR-NC." (PMID 29483929, 2018).